IL6 (interleukin 6)
Diseases named in the same sentence as IL6 in open-access papers (continued):
Sharing a sentence is not in itself a finding about the gene and the disease.
Obesity (continued). "A single IL-6 or a combination of CRP-IL-6 and CRP-fibrinogen plays an important role in the prediction of diabetes, and the main reason for the increase in inflammatory markers may be obesity, through which diabetes risk increases." (PMID 39325793, 2024). "Obesity leads to the accumulation of lipids in adipocytes and is responsible for triggering the release of inflammatory markers such as tumor necrosis factor-α (TNFα), interleukin-6 (IL-6), and C-reactive protein (CRP) and for insulin resistance." (PMID 39759127, 2024). "IL-6 is secreted in brown adipocytes, making these cells unable to regulate the metabolism of substances such as glucose and decompose fat, ultimately leading to obesity." (PMID 39830328, 2024). "While IL-6 released from skeletal muscle mediates the pleiotropic metabolic benefits of exercise, chronic and excessive production of IL-6 from adipose tissue in obesity contributes to metabolic inflammation and insulin resistance." (PMID 38321233, 2024). "The macrophages and adipocytes are the major TNFα and IL-6 sources in individuals with obesity." (PMID 38279016, 2024). "Inflammation caused by an imbalance of interleukin 6, 8 and TNF-alpha secreted by adipose tissue is thought to weaken and dilate vessels and may explain the role of obesity in aneurysm formation and weight loss may reduce the aortic diameter." (PMID 38674307, 2024). "However, there is currently not enough information to define inflammatory factors, such as interleukin-6, as prognostic tools for investigating pregnancies with either pre-existing type 2 diabetes or obesity." (PMID 38893732, 2024). "Adipose tissue in obesity secretes proinflammatory cytokines like TNFα and IL-6." (PMID 39859981, 2024). "Owing to IL-6-mediated effects on ATM proliferation, polarization and recruitment, IL-6 and mannose receptor 1 expression sustain potential targets to rescue insulin sensitivity in obesity and the role of IL-6 as a pro-inflammatory clinical parameter should be revised." (PMID 38482013, 2024). "Interleukin 6 (IL-6), another cytokine produced by adipocytes, has anti-inflammatory effects in some situations; elevated levels of IL-6 in obesity can contribute to chronic low-grade inflammation and insulin resistance, further impacting metabolic and cardiovascular functions." (PMID 39411599, 2024). "Additionally, obesity is often accompanied by a chronic inflammatory state, with elevated levels of inflammatory cytokines such as IL-6." (PMID 39767857, 2024). "H. pylori may contribute to metabolic disorders and obesity by producing pro-inflammatory cytokines, such as tumor necrosis factor-α, interleukin (IL)-1, IL-6, and IL-8, which increase inflammatory responses and promote insulin resistance." (PMID 38971751, 2024). "By increasing faecal butyric acid levels and hepatic SOD and GPx activity, with a decrease in lipid peroxidation and suppressed expression of TNFα, IL-6, iNOS, and NF-κB levels, purple maize anthocyanin efficiently demonstrated anti-obesity efficacy in C57BL/6 mice fed a high-fat diet." (PMID 39125340, 2024). "In obesity, circulating IL-6 is elevated in line with TNF-α serum levels." (PMID 38482013, 2024). "Notably, IL-6 knockout mice develop mature-onset obesity implicating IL-6 as an essential player in the carbohydrate and lipid metabolism." (PMID 39723211, 2024). "However, plasma IL-6 concentrations in males in obesity groups 1 and 2 compared to controls 1 and 2 were even higher." (PMID 39408365, 2024). "However, mice lacking Il6 expression develop obesity, and both endogenous and exogenous IL-6 has anti-obesity effects, since IL-6 increases lipolysis and heat generation from stored fat." (PMID 38474057, 2024). "Therefore, this study aimed to assess the safety of utilizing miR-130b-MVs for obesity treatment, revealing an upward trend in plasma levels of IL-6 and TNF-α after miR-130b-MV injection." (PMID 39591339, 2024).
Obesity (continued). "Likewise, studies incorporating bariatric surgery and its role in obesity show a decrease in adiposity and in serum levels of IL-6, and TNF-α." (PMID 39184030, 2024). "Oxidative stress and chronic inflammation may be increased with obesity, as well as the levels of IL-1β, IL-6 and TNF-α, which contribute to the development of lung injury." (PMID 38650653, 2024). "Furthermore, the intricate interplay between chronic low-grade inflammation and insulin resistance, as well as obesity, underscores the significance of IL-6 in the pathophysiology and disease progression." (PMID 38667300, 2024). "The levels of TNF-α, IL-1β, and IL-6 are elevated in obesity." (PMID 39063610, 2024). "In the state of obesity, the pro-inflammatory adipokines derived from adipose tissue are overexpressed, and among which, increased production and secretion of inflammatory mediator IL-6 is marked." (PMID 39180618, 2024). "Numerous genetic variations linked to obesity-related asthma have been pinpointed in research studies, encompassing ADIPOQ, retinoid-related orphan receptor C (RORC), IL17A, TNF-α, beta-2 adrenergic receptor (ADRB2), and IL-6." (PMID 37834850, 2023). "Interactions between CRC-associated obesity and inflammation regulated by AT macrophages adjacent to the tumor, which secrete pro-inflammatory cytokines, e.g., TNF-α, monocyte chemoattractant protein-1 (MCP-1) and IL-6 have long been highlighted." (PMID 36835075, 2023). "Since proinflammatory cytokines, including TNF and IL-6, are secreted by white adipose tissue, it is thought that excess adipose mass in patients with RA and obesity may affect treatment response by increasing the level of these cytokines." (PMID 38813042, 2023). "Obesity is characterized by prolonged low-grade tissue and systemic inflammation mediated by high serum concentrations of circulating pro-inflammatory cytokines, including IL-6." (PMID 37569456, 2023). "Obesity generates low-grade systemic inflammation with an increase in IL-6." (PMID 38140340, 2023). "Indeed, LPS-treatment and obesity state increased TNFα, IL-1β, and IL-6 expression, both at mRNA and protein levels, in type I TBC." (PMID 37373472, 2023). "IL-6 is a cytokine with pleiotropic actions secreted by several cell types, including adipocytes, and its plasma levels are significantly upregulated during obesity." (PMID 36831188, 2023). "Additionally, the cytokine IL-6 seems to have an association with inflammation, obesity by increasing the activation of the AKT pathway, and IR through excess IL-6 synthesis." (PMID 37062827, 2023). "Furthermore, the reduction of IL-6 levels in GCF after NSPT is also statistically significant in patients with obesity in a 3-month follow-up period." (PMID 37798684, 2023). "Indeed, obesity promotes cancer through mechanisms involving ROS and is associated with the presence of adipokines, VEGF, TNFα and IL-6." (PMID 36670988, 2023). "Systemically, increased adipose tissue accumulation, as seen in obesity, can lead to increased production of interleukin 6 (IL-6), interleukin IL-1β (IL-1β) and tumor necrosis factor (TNF-α), pro-inflammatory cytokines able to disrupt the immune response at the maternal–fetal interface." (PMID 37111410, 2023). "IL-6 regulates energy expenditure in obese individuals and may also act as a first homeostatic response to low-grade inflammation related to obesity." (PMID 37781401, 2023). "Among them, IL-6 and IL-1β are crucial for obesity-related HCC." (PMID 37266440, 2023). "PLA2 also showed a weak but significant correlation with obesity, and the level of IL-6 correlates with the presence of pulmonary circulatory disorders, pulmonary artery pressure, peripheral vascular disorders, coagulopathy, renal insufficiency, rheumatoid arthritis, collagen, and vascular diseases." (PMID 36982611, 2023).
Obesity (continued). "Importantly, plasma viral load has been associated with other indicators of severity, such as inflammatory mediators and IL-6, which are typically elevated in patients with obesity, promoting the cytokine storm." (PMID 37686837, 2023). "Secondly, adipocyte-derived factor, the metabolic alteration in adipose tissue in the setting of obesity, results in an elevated circulating level of adipocyte-derived inflammatory cytokines, enclosing tumor necrosis factor-α, interleukin-6, angiotensinogen, and aldosterone-stimulating factors." (PMID 37464282, 2023). "Research suggests that patients with high BMI levels may experience reduced efficacy of benralizumab due to systemic inflammation caused by elevated levels of obesity-related cytokines like TNF-α, IL-6, and leptin." (PMID 38053108, 2023). "TNF-α and IL-6, which are generated by adipose tissue as adipokines, encourage low-grade systemic inflammation, which has been linked to chronic, detrimental conditions, such as T2DM, insulin resistance, and obesity." (PMID 38004306, 2023). "It was supported by elevated circulating IL-6 in patients with obesity and the onset of diabetes." (PMID 37113481, 2023). "In patients with obesity, IL6 is overproduced by white adipose tissue." (PMID 36986146, 2023). "Besides, they can act on the most diverse proteins, such as tyrosine phosphatase 1B, AMP-activated protein kinase, interleukin 6 and chemokine ligand 2 and pancreatic lipase, that are proteins involved in the metabolism of both diseases, obesity, and DM." (PMID 37058011, 2023). "In addition, 3 months of low-volume high-intensity interval cycling (80%–95% HRmax, 2 sessions/week) meaningfully reduced CRP and IL-6 while increasing VO2max in metabolic syndrome patients (mean age 53.7 years) with obesity." (PMID 37608837, 2023). "Morbid obesity leads to increased interleukin-6 levels, promoting plaque accumulation and rupture." (PMID 37431356, 2023). "In the presence of obesity, therefore, it seems that myocytes also release proinflammatory cytokines (myosins), such as IL-6 and TNFα, in a synergic effect of the activity of myocytes and adipocytes on metabolic dysregulation, aggravating insulin resistance and inflammation." (PMID 36626317, 2023). "In the subgroup analysis that compared serum levels of IL-6 (pg/mL), five studies showed that the baseline IL-6 levels of people with obesity and periodontitis (OP) were higher than those of normal-weight patients with periodontitis (NP) before treatment (MD = 0.51, CI = 0.09–0.93)." (PMID 37798684, 2023). "There is an influence of obesity on IL-6 levels, as its levels are positively correlated with BMI." (PMID 36769452, 2023). "Increased concentrations of IL-6 occur in patients with obesity and type 2 diabetes." (PMID 36615169, 2023). "In studies that induced obesity in rodents, a reduction of plasmatic glutathione dismutase and superoxide dismutase, which are markers of antioxidant enzymes, was observed, associated with high levels of plasmatic TNF-α and IL-6 as pro-inflammatory markers." (PMID 36986038, 2023). "Higher levels of IL-6 have been reported in obesity, diabetes, and insulin resistance." (PMID 37168278, 2023). "The pro-inflammatory state of obesity is widely agreed upon, and adipose tissue is likely to contribute to chronic persistent low-grade systemic inflammation by the production of inflammatory cytokines such as IL6." (PMID 37479793, 2023). "Later, it was found that adipose tissue secretes different types of “adipocytokines” including inflammatory interleukin-6 (IL-6) which may link obesity to other metabolic and chronic diseases." (PMID 38201900, 2023). "In an in vitro study, PC12 cells treated with H2O2 reduce pro-inflammatory markers associated with obesity, such as C-reactive protein (CRP), interleukin (IL)-6, and tumor necrosis factor (TNF)-α, leading to reduced oxidativestress-induced neurotoxicity in PC12 cells treated with H2O2." (PMID 37835263, 2023).
Obesity (continued). "Cytokines previously associated with increased inflammation, obesity, and metabolic diseases (IL-1β, IL-6, IFN-β, IL-1RA, and IL-17F) were numerically higher but not significantly different in mothers with obesity compared to mothers without obesity." (PMID 38068816, 2023). "Participants with high PBF or abdominal obesity had higher levels of IL-6, but no independent association was found between IL-6 levels and obesity markers." (PMID 37375693, 2023). "Furthermore, a complex interaction between inflammation and NAFLD has been shown among children with obesity, for which inflammatory cytokines, such as IL-1β, IL-6 and IL-17, have been recently described as markers for NAFLD risk." (PMID 36837520, 2023). "Moreover, considering that chronic inflammation is associated with obesity and can further worsen IR, we measured the levels of TNF-α, IL-1β, and IL-6 in visceral adipose tissue." (PMID 37513467, 2023). "Obesity and IR promote the transition of macrophages from the anti-inflammatory state M2 to the pro-inflammatory state M1, which leads to the production of interleukin-1 (IL-1), interleukin-6 (IL-6), and tumor necrosis factor-alpha (TNF- α)." (PMID 37893164, 2023). "Moreover, excess myocardial collagen deposition is linked to high circulating levels of IL-6 and TNF-α in patients with obesity and heart failure." (PMID 37383542, 2023). "In particular, obesity-promoted HCC initiation depends on increased levels of IL-6 and TNF-α." (PMID 36845555, 2023). "In the aorta, early overfed rats also showed increased gene expression of the pro-inflammatory cytokines IL-6 and TNFα compared to control rats, possibly as a result of increased infiltration of macrophages into the arterial tissue as is reported in other obesity models." (PMID 37833890, 2023). "Moreover, inhibition of SHP2, PDHA1, or ROS decreased the secretion of the pro-inflammation cytokine, IL-6, a key mediator of obesity-mediated PDAC hallmarks." (PMID 36074246, 2023). "Given that obesity is considered a chronic state of low-grade inflammation, it was not surprising to observe considerable increases in the expression of inflammatory cytokines, IL-1 and IL-6, in adipocytes and macrophages in Negr1−/− mice." (PMID 37187893, 2023). "For example, the important relationship between specific steps in the development of colon cancer and obesity-induced inflammation has been pointed out to be mediated by inflammatory cytokines secreted by macrophages, such as interleukin 6 (IL-6) and tumor necrosis factor-alpha (TNF-α)." (PMID 36982615, 2023). "Another limitation was the nature of our study design, which did not allow the assessment of cause-effect relationships between selected measures of obesity (BMI, WC, RFM, VAI, WHtR) and parameters of chronic inflammation (CRP, TNF-α, IL-6) in perimenopausal healthy women." (PMID 37375693, 2023). "Thus, similarly to other adipokines like leptin, resistin and IL-6 overproduced by the adipose tissue during obesity, MCP-1 plays a causal role in inflammation, insulin resistance and atherosclerosis during obesity." (PMID 38136564, 2023). "In addition, IL-6, TNF-α, and CRP are repeatedly found to be elevated in a myriad of conditions linked to inflammation, such as obesity and smoking." (PMID 37213604, 2023). "IL-6 expression has been already correlated with the expression of several inflammatory markers in subcutaneous adipose tissue from obese individuals, and adipocytes can secrete IL-6 in response to obesity, leading to an increase in adipose tissue macrophage accumulation." (PMID 37569775, 2023). "Previous studies suggest that increased levels of interleukin-6 (IL-6) and TNF-α may be linked to obesity and insulin resistance, signifying their involvement in ER stress and reduced insulin sensitivity." (PMID 38140341, 2023). "The increase in IL-6 suggests obesity-induced BMSC senescence, which might be associated with the IL-6/STAT3 pathway." (PMID 36902259, 2023).
Obesity (continued). "Obesity is a chronic inflammatory disorder in which necrotic adipocytes attract inflammatory cells and release inflammatory cytokines like TNF-α; PCOS is also associated with higher levels of M1 macrophages and inflammatory cytokines like TNF-α and IL-6." (PMID 37215125, 2023). "Inflammatory cytokines, including interleukin (IL)-6, tumor necrosis factor alpha (TNFα), and IL-1β, have been shown promote the expansion of myeloid progenitor cells and are produced by both adipocytes and macrophages in obesity." (PMID 38041006, 2023). "The tissue concentration of IL-6 also increases during acute inflammation and obesity." (PMID 40589521, 2023). "During obesity-induced insulin resistance, higher levels of tumor necrosis factor (TNF)-α and interleukin (IL)-6 secreted by adipose tissue may explain the associations of coagulopathy and endothelial dysfunction with insulin resistance." (PMID 37142990, 2023). "Obesity is characterised by excessive adiposity, and increased concentrations of the pro-inflammatory adipokines tumour necrosis factor alpha (TNFα) and interleukin-6 (IL-6), leading to a chronic low-grade state of inflammation." (PMID 37228106, 2023). "In brief, obesity, characterized by chronic low-grade inflammation (elevated IL-6), increases hepcidin (an iron-regulating peptide hormone), reducing intestinal iron absorption, and eventually, leading to systemic iron deficiency and/or iron restricted erythropoiesis." (PMID 36796481, 2023). "IL-6 and the adipokine leptin are key mediators of inflammation in obesity." (PMID 37841878, 2023). "This current systematic review and meta-analysis investigated the effect of dietary ALA on CVD risk factors, including inflammatory markers (CRP, IL-6, and TNF-α in serum), BP, and blood lipid profile (TG, TC, LDL cholesterol, and HDL cholesterol in serum) in patients with overweight or obesity." (PMID 37778442, 2023). "Although the mechanism leading to impairment of muscle dysfunction in obesity remains unclear, the proinflammatory cytokines present in the muscles such TNFα, IL-6 which are elevated in obesity has been found to be reduced by exercise." (PMID 37576965, 2023). "Thus, alimentary-induced obesity enhanced the release of pro-inflammatory cytokines, namely IL-1β and IL-6, into the blood." (PMID 37892420, 2023). "Thus, there exist a correlation between JAK‐STAT‐SOC3 and IL‐6 signalling in obesity and chronic inflammatory skin diseases which is less explored." (PMID 37275420, 2023). "Obesity is associated with an increase in the secretion of adipocytokines, such as TNF-α, leptin, resistin, IL-1β or IL-6, by immune cells as well as adipocytes, which leads to the progress of insulin resistance through a number of processes, including the activation of Ser/Thr kinases." (PMID 36826001, 2023). "Furthermore, increasing levels of inflammatory cytokines like IL-1, IL-6, and TNF-α are associated with obesity, and these cytokines are secreted by the adipose tissue." (PMID 37571429, 2023). "Meanwhile, obesity elevates the concentration of IL-6 in the WT mouse-derived BMSC supernatant." (PMID 36902259, 2023). "Obesity and overweight are identified as risk factors for flare in patients with SLE, by the expression of inflammatory cytokines such as tumor necrosis factor-alpha (TNF-α) and interleukin 6 (IL-6)." (PMID 37384711, 2023). "Interleukin-6 (IL-6) is known as a key regulator of adipose homeostasis in obesity." (PMID 37252399, 2023). "Additionally, in obesity, elevated levels of interleukin 6 (IL-6) and tumor necrosis factor alpha (TNF-α) are observed." (PMID 37375693, 2023). "Many cytokines, particularly Th1-derived cytokines such as TNF-α, IFN-γ, IL-6, and IL-2, are increased when obesity is present, resulting in chronic low-grade inflammation that may predispose individuals to hypersensitive reactions." (PMID 36614274, 2023).